LMNA (lamin A/C)
Diseases named in the same sentence as LMNA in open-access papers (continued):
Sharing a sentence is not in itself a finding about the gene and the disease.
dilated cardiomyopathy (continued). "Mutations in LMNA cause a plethora of disease phenotypes including skeletal muscular dystrophy and dilated cardiomyopathy." (PMID 36120560, 2022). "Mutations in LMNA have been shown to cause autosomal, dominant, severe heart disease accounting for 10% of dilated cardiomyopathies." (PMID 35563877, 2022). "We found that mRNA levels of lamins A and C are increased in fibroblasts obtained from a dilated cardiomyopathy patient with a heterozygous p.S143P LMNA mutation." (PMID 36111332, 2022). "Mutations in the LMNA gene, encoding Lamin A/C (LMNA), are established causes of dilated cardiomyopathy (DCM)." (PMID 35891706, 2022). "Lamin A/C gene mutations cause dilated cardiomyopathy associated with cofilin-1 phosphorylation and actin destabilization." (PMID 36550158, 2022). "Here, we characterized a truncated LMNA variant, Q517X, a pathogenic LMNA variant shown to be associated with dilated cardiomyopathy with conduction abnormalities and neuromuscular disorders." (PMID 35846372, 2022). "In summary, we show for the first time an actin-microtubule cytoskeletal interplay mediated by cofilin-1 and MRTF-A/SRF, promoting the dilated cardiomyopathy caused by LMNA mutations." (PMID 36550158, 2022). "LMNA-related dilated cardiomyopathy is an inherited heart disease caused by mutations in the LMNA gene encoding for lamin A/C." (PMID 34360639, 2021). "In knockout mouse models of dilated cardiomyopathy with the LMNA H222P mutation in response to mechanical stress in cardiomyocytes, activation of the MAPK signaling pathway was observed, in which kinases such as ERK1/2 and JNK were involved." (PMID 34722546, 2021). "Recently, several studies have observed an association between LMNA mutations and high risk of various cardiac disorders, which include dilated cardiomyopathy that reduces the heart’s ability to supply blood and causes heart failure." (PMID 34302027, 2021). "For example, a specific mouse model that had the mutation of the gene LMNA p.H222P offered an insight on cardiac involvement, associating the development of dilated cardiomyopathy with cardiac conduction defects." (PMID 34066119, 2021). "Mutations of LMNA gene can cause a wide array of heart diseases, such as atrial arrhythmia, atrioventricular block, sinus bradycardia, and dilated cardiomyopathy (DCM)." (PMID 33407844, 2021). "Other diseases of the heart and skeletal muscles associated with mutations in the LMNA gene were soon described: dilated cardiomyopathy 1A and limb-girdle progressive muscular dystrophy 1B." (PMID 34722546, 2021). "Similar to JNK, the activation of p38 promotes cardiac remodeling and fibrosis and is associated with lamin A/C mutation-induced dilated cardiomyopathy." (PMID 32195266, 2020). "Dilated cardiomyopathy can result from mutations in LMNA, encoding the nuclear intermediate filament proteins lamin A/C." (PMID 31622279, 2019). "Mutation of LMNA, encoding Lamin A/C nuclear proteins, cause dilated cardiomyopathy and conduction disorders." (PMID 31118417, 2019). "By 2000, it was clear that both dilated cardiomyopathy and partial lipodystrophy were caused by LMNA mutations." (PMID 29861492, 2018). "Mutations in the LMNA gene are a common cause (6–8%) of dilated cardiomyopathy (DCM) leading to heart failure, a growing health care problem worldwide." (PMID 29702688, 2018).
dilated cardiomyopathy (continued). "Mutations in the human LMNA that cause dilated cardiomyopathy with conduction defects are often point mutations resulting in amino acid substitutions in residues conserved among species." (PMID 29575479, 2018). "It was originally proposed that Emery-Dreifuss muscular dystrophy, limb girdle muscular dystrophy type 1B, and dilated cardiomyopathy 1A resulted from distinct LMNA mutations." (PMID 29861492, 2018). "Mutations in the lamin A/C gene (LMNA) were reported to cause an autosomal dominant inherited form of dilated cardiomyopathy (hereafter referred to as LMNA cardiomyopathy)." (PMID 29849091, 2018). "The association with LMNA mutations is much more common in patients with dilated cardiomyopathy and conduction system disorders being present in 30% of such subsets." (PMID 27504462, 2016). "It has been observed that the majority of mutations in FPLD 2 affect the C-terminal domain of the lamin A/C protein, whereas alterations responsible for dilated cardiomyopathy and other diseases are usually clustered in the rod domain of the protein." (PMID 26976018, 2016). "Mutations in the lamin A/C gene (LMNA) were associated with dilated cardiomyopathy (DCM) and, recently, were related to severe forms of arrhythmogenic right ventricular cardiomyopathy (ARVC)." (PMID 25837155, 2015). "Dilated cardiomyopathy patients with LMNA mutations have poor prognosis, however considerable clinical variability is present among family members." (PMID 23702046, 2013). "LMNA mutations are most frequently involved in the pathogenesis of dilated cardiomyopathy with conduction disease." (PMID 23702046, 2013). "The goal of this study was to identify LMNA mutations, estimate their frequency among Polish dilated cardiomyopathy patients and characterize their effect both in vivo and in vitro." (PMID 23702046, 2013). "Mutations in Lamin A/C gene (LMNA) causing dilated cardiomyopathy are related to a decrease in Cx43 levels." (PMID 22536530, 2012). "Mutations in the LMNA gene are well-established causes of dilated cardiomyopathy: this interaction may also help explain the development of this phenotype in TMEM43 patients." (PMID 40869437, 2025). "Notably, in 50% of individuals carrying LMNA variants, the onset of AF precedes the development of dilated cardiomyopathy or other ventricular arrhythmic-related cardiomyopathies by several years, indicating that LMNA variants drive AF." (PMID 40605555, 2025). "LMNA mutations cause muscular dystrophies, dilated cardiomyopathy, and other diseases." (PMID 38778055, 2024). "LMNA is one of the leading causative genes of genetically inherited dilated cardiomyopathy (DCM)." (PMID 34250035, 2021). "Different mutations in LMNA are responsible for a variety of disorders affecting a variety of organs, including dilated cardiomyopathy, familial partial lipodystrophy, Emery-Dreifuss muscular dystrophy, limb girdle muscular dystrophy, Charcot-Marie-Tooth disease, and restrictive dermopathy." (PMID 34308436, 2021). "LMNA mutations can also lead to dilated cardiomyopathy (DCM)." (PMID 33316938, 2020). "In addition, a comparable role for DNA damage has been observed in other cardiac diseases, including LMNA mutation-induced dilated cardiomyopathy, peripartum cardiomyopathy and coronary artery disease." (PMID 32411727, 2020).
dilated cardiomyopathy (continued). "The first reports that associate LMNA mutations to cardiac diseases date back to 1999: these reports represented a revolution in the field, identifying for the first time LMNA mutations as responsible for dilated cardiomyopathy (DCM) associated with conduction system disease." (PMID 32719615, 2020). "LMNA-related DCM with conduction defects is one of the most common forms of inherited dilated cardiomyopathy, second only to DCM associated with mutations in sarcomere protein genes, with an estimated 5 to 10% of cases associated with a heterozygous LMNA mutation." (PMID 32698886, 2020). "Mutations in LMNA that give rise to Lamin A/C G449V cause congenital muscular dystrophy, which is characterized by skeletal muscle defects in childhood and age‐dependent dilated cardiomyopathy." (PMID 29575479, 2018). "One gene associated with dilated cardiomyopathy, LMNA, is associated with several other disorders." (PMID 30011878, 2018). "Moreover, LMNA mutations are a common cause (ca. 6–8%) of dilated cardiomyopathy (DCM), a major reason of severe heart failure." (PMID 29702688, 2018). "Dilated cardiomyopathy with mutations in LMNA are associated with poor prognosis." (PMID 27504462, 2016). "Supporting this assumption, the observation of impaired autophagy in our model is similar to those obtained in some LMNA-related murine models: such as Lmna knockout mice (dilated cardiomyopathy and muscle dystrophy) and Zmpste24-deficient mice (extreme phenotype of premature aging)." (PMID 24753226, 2014). "Interestingly, only homozygous—but not heterozygous—knock-in mouse models for either muscular dystrophy-associated or cardiac-specific LMNA mutations display dilated cardiomyopathy with conduction defects and premature death." (PMID 22905185, 2012). "Phenotypic expression of lamin AC-dilated cardiomyopathy (LMNA-DCM) and cardiac sarcoidosis (CS) at times presents with similar clinical findings, including arrhythmia, conduction abnormalities, and heart failure." (PMID 40225500, 2025). "From a genetic perspective, mutations in genes such as LMNA, SCN5A, and FLNC have been reported as forms of dilated cardiomyopathy associated with electrical instability." (PMID 40680495, 2025). "LMNA mutations can display significant intra- and inter-family variability, with different members of the same family having an EDMD, LGMD or dilated cardiomyopathy phenotype." (PMID 39501809, 2024). "Dominant mutations in LMNA, which encodes lamin A/C, can cause a wide variety of syndromes, including EDMD, dominantly inherited LGMD and dilated cardiomyopathy." (PMID 39501809, 2024). "Among these is lamin A/C (LMNA), the most pleiotropic human gene with ~500 VUS causing over a dozen distinct clinical phenotypes including dilated cardiomyopathy (DCM)." (PMID 35859585, 2022). "For example, mutations in lamin A/C (LMNA) gene can result in Emery-Dreifuss muscular dystrophy, dilated cardiomyopathy, Charcot-Marie-Tooth (CMT) disease and spinal muscular atrophy." (PMID 33653295, 2021). "There are 41 known LMNA mutations, as follows: 23 of them cause autosomal dominant Emery–Dreifuss muscular dystrophy (EDMD2), 8 of them cause dilated cardiomyopathy and 1 mutation causes autosomal recessive Emery Dreifuss (EDMD3)." (PMID 34356086, 2021). "Some special gene mutations in dilated cardiomyopathy such as DSP, LMNA, SCN5A, and FLNC have an arrhythmia rate of more than 30%35." (PMID 31953454, 2020). "Dilated cardiomyopathy (DCM) has been attributed to mutations in sarcomere and sarcolemma-related genes, including titin, lamin A/C (LMNA), MHC, and cardiac troponins." (PMID 31871214, 2020).
dilated cardiomyopathy (continued). "In inherited, i.e. non‐ischaemic, dilated cardiomyopathy, the genetic background is very important, with LMNA (Lamin A/C) and PLN (Phospolamban) leading to highly arrhythmic substrates." (PMID 32782627, 2020). "Although patients with CCM had rare variants in several established dilated cardiomyopathy (DCM) genes (BAG3, LMNA, MYH7, TCAP, TNNT2, and TTN), only variants in TTN, which encodes titin, were significantly increased." (PMID 30987448, 2019). "Research on lamin A/C mutations linked to Emery-Dreifuss muscular dystrophy (EDMD) and dilated cardiomyopathy (DCM) further underscores a role of lamin A/C in nuclear mechanics." (PMID 27803806, 2016). "The lamin A/C gene (LMNA) is so far the most significant disease gene identified clinically for dilated cardiomyopathy (DCM)." (PMID 23158097, 2012). "For example, variants in the LMNA gene can lead to dilated cardiomyopathy, arrhythmias and conduction abnormalities, or even non-cardiac diseases such as progeria and neuropathies." (PMID 40441529, 2025). "Genetic screening for dilatative cardiomyopathy-associated genes revealed no mutations, in particular, no mutation of the lamin A/C (LMNA) gene." (PMID 40191636, 2025). "Genetic testing revealed a novel likely pathogenic mutation of the LMNA gene (c.513G>A, exon 2) not previously associated with dilated cardiomyopathy, and the patient underwent guideline direct treatment for dilated cardiomyopathy." (PMID 39411178, 2024). "Mutations in the LMNA gene encoding Lamin A and C (Lamin A/C), major components of the nuclear lamina, cause laminopathies including dilated cardiomyopathy (DCM), but the underlying molecular mechanisms have not been fully elucidated." (PMID 37058558, 2023). "A specific LMNA mutation manifesting as dilated cardiomyopathy (dCMP), and iron metabolism disorder has not been reported." (PMID 37303410, 2023). "Dilated cardiomyopathy (DCM) is a serious cardiac heterogeneous pathological disease, which may be caused by mutations in the LMNA gene." (PMID 33407844, 2021). "In addition, circulating miR-143 levels were found to be significantly higher in the serum of children with dilated cardiomyopathy and miR-145 levels were reportedly higher in the plasma of lamin A/C-related dilated cardiomyopathy patients." (PMID 32855642, 2020). "Mutations in LMNA give rise to a host of diseases that affect striated muscle, which lead to dilated cardiomyopathy that may or may not be associated with skeletal muscle defects." (PMID 37624850, 2023). "ERK1/2 is hyperactivated in in vitro and in vivo models with LMNA mutations, and recent findings have provided proof of principle for ERK1/2 inhibition as a therapeutic option to prevent or delay the onset of heart failure in patients with dilated cardiomyopathy caused by mutations in LMNA3–6." (PMID 36550158, 2022). "Mutations in the Lamin A/C (LMNA) gene present pleiotropic effects and may cause a spectrum of distinct disorders, such as striatal muscle diseases, peripheral neuropathy, partial lipodystrophy syndromes, and dilated cardiomyopathy (DCM) associated with conduction system disease." (PMID 35449878, 2022). "Genetic screening for dilatative cardiomyopathy (DCM)-associated genes revealed no mutations, in particular no mutation of the lamin A/C (LMNA) gene." (PMID 40191636, 2025).
progeria (105 papers, 2005 to 2026). "Patient‐derived iPSCs, for example, from progeria patients with LMNA mutations, enable an in‐depth study of aging in human genetics to test drugs like lonafarnib." (PMID 41556081, 2026). "Nevertheless, given the known role of LMNA in progeroid syndromes and the exclusion of other common causes, the p.Glu262Gly mutation stands as the most likely significant contributor to the severe valvular disease observed in this family." (PMID 41357091, 2025). "Mandibuloacral dysplasia type A (MADA) is a rare progeroid syndrome associated with mutations in the Lamin A/C (LMNA) gene, primarily affecting skeletal, cutaneous, and adipose tissues." (PMID 41357091, 2025). "This classification is in line with the description of progeroid laminopathies which are caused by mutations in LMNA other than 1824C>T, as well as the occurrence of atypical progeroid syndromes caused by non-LMNA mutations (see Discussion)." (PMID 41000886, 2025). "Hutchinson-Gilford syndrome, the most studied progeroid syndrome, arises due to a mutation in the lamin A gene or LMNA, resulting in the production of mutant LMNA protein or progerin." (PMID 40231186, 2025). "Other progeroid syndromes can be caused by mutations in LMNA other than c.1824C>T and are referred to as progeroid laminopathies or can be due to non-LMNA mutations which are classified as atypical progeroid syndromes." (PMID 41000886, 2025). "Mandibuloacral dysplasia type A (MADA) represents a rare segment of the progeroid syndromes spectrum, stemming from mutations in the LMNA gene and primarily impacting skeletal, cutaneous, and adipose tissues." (PMID 41357091, 2025). "Additional variants affecting other subdomains of the α-helical rod region, such as LMNA c.412G>C (p.Glu138Gln) within coil 1B, have also been linked to atypical progeria primarily manifesting as premature valvular heart disease." (PMID 41300702, 2025). "Another case involves a male patient with a progeroid syndrome with two different variants in the LMNA gene (exon 9 and 10) also had healthy parents with only one of those variants." (PMID 39125589, 2024). "Among the progeroid syndromes, those associated with LMNA variants are particularly significant due to their resemblance to aspects of ageing and range from the mild acceleration observed in MADA to severe acceleration in HGPS." (PMID 39273270, 2024). "Firstly, the Hutchinson–Gilford progeria syndrome (HGPS), also known as accelerated aging syndrome or progeria, is caused by mutations in the LMNA gene that encodes Lamin A/C, and it is tightly related to the structure of the nuclear envelope and the pores." (PMID 39408822, 2024). "Of note, it has been shown that, in the context of progeria (due to LMNA/C mutations), NE destabilizations are associated with perturbed nuclear transport, essentially explained by alterations in the composition of NPC." (PMID 38132118, 2023). "Progeria, a laminopathy, was caused by the mutation of lamin A which, encoded by the LMNA gene, supports the protein complexes that help keep the cell nucleus stable and the genomes intact." (PMID 36196312, 2022). "Several studies have also clarified the underlying mechanism of LMNA mutations in progeria-induced aging and have shown the key function of lamin A/C in promoting the differentiation of myocytes and adipocytes." (PMID 36552752, 2022). "A notable example is the identification of the p.D300N (p.Asp300Asn) mutation in the LMNA gene in cases with the progeroid syndrome, including a patient in whom the cardiovascular system was predominant if not the exclusive organ involved." (PMID 35531366, 2022). "Several genetic mutations of lamin A/C result in defects in the nuclear envelope, leading to progeroid syndrome or muscular dystrophies." (PMID 35338226, 2022). "In 2003, we and others independently identified a recurrent de novo point mutation (c.1824C>T, p.G608G) in the LMNA gene (1q21) encoding A-type lamins as the most frequent cause of classical progeria." (PMID 35203262, 2022).